RYR2 (ryanodine receptor 2)
Diseases named in the same sentence as RYR2 in open-access papers (continued):
Sharing a sentence is not in itself a finding about the gene and the disease.
cardiomyopathy (61 papers, 2007 to 2025). A disease of the heart muscle or myocardium proper. "For example, RyR2 is located in Purkinje cells of the cerebral cortex and excessively active “leaky” RyR2 channels associated with mutations causing cardiomyopathies can result in seizures." (PMID 38203604, 2023). "ARVD2 (or arrhythmogenic right ventricular cardiomyopathy (ARVC)) is a cardiomyopathy linked to missense mutations of the RyR2 gene." (PMID 35457253, 2022). "Further, age-dependent biochemical remodeling of the ryanodine receptor 2 (RYR2) in the heart that lead to “leaky” RYRs and a subsequent increase of the SR Ca2+ leak has been shown to play a role in cardiomyopathy caused by LMNA H222P mutation." (PMID 34408666, 2021). "The majority of the VUS has been identified in genes previously having been reported to be associated with cardiac channelopathies (SCN5A, AKAP9, RYR2) and cardiomyopathies (RBM20, RAF1, DSG2)." (PMID 33789662, 2021). "The modest reductions in RNA levels in the mouse orthologs of two of the known genetic causes of cardiomyopathy in humans (Ttn and Ryr2) are interesting but difficult to interpret." (PMID 30856165, 2019). "In an attempt to understand the disease mechanism underlying RyR2-associated cardiomyopathies, in the present study, we generated a mouse model in which the entire exon-3 and part of the introns 2 and 4 were deleted using the knock-in approach." (PMID 24743769, 2014). "HL-1 cells have been successfully used to investigate other arrhythmogenic cardiomyopathies including those due to RyR2 mutations (ARVC2), mutations of the desmosomal gene desmocollin-2 (ARVC11) and si-RNA studies of the desmosomal gene plakophillin-2 (ARVC9)." (PMID 25343256, 2014). "This was an unexpected finding because a “leaky” RyR2 at diastolic Ca2+, caused by phosphorylation of RyR2 at Ser2815, has been implicated in cardiomyopathies." (PMID 25093823, 2014). "Among GEE results for HF was rs939698 (p = 3.6 × 10-4) in RYR2, which has been implicated in arrhythmogenic right ventricular dysplasia/cardiomyopathy, a rare familiar cardiomyopathy." (PMID 17903304, 2007). "However, in contrast to CPVT-associated RyR2 mutations, there are few models that express cardiomyopathy-associated RyR2 mutations." (PMID 24743769, 2014). "The RyR2 NH2-terminal region may thus be an important determinant for termination of Ca2+ release, abnormalities in which are common in RyR2-associated cardiomyopathies." (PMID 23805105, 2013). "Therefore, we utilized the RyR2-PBmice to evaluate the effects of the PB transposon inserted into the RyR2 gene on cardiac functions, attempting to further understand the physiological dysfunction underlying RyR2-associated cardiomyopathies." (PMID 31143551, 2019). "Moreover, mutations affecting RyR2 function have been associated with cardiomyopathies." (PMID 30050558, 2018). "In dystrophic mice, inhibition of PKA-mediated phosphorylation of RyR2 reduced SR calcium leak and in turn prevented cardiomyopathy." (PMID 39056750, 2024). "Considering rare variants for each cardiomyopathy type, in ARVC patients, the highest number of rare variants was found in TTN and RYR2 genes (4 variants) followed by OBSCN and PKP2 (3 variants)." (PMID 28750076, 2017). "A pan cardiomyopathy microarray designed to identify mutations in genes associated with cardiomyopathy and CPVT revealed three mutations: ryanodine receptor (RyR2) Arg169Gln, calsequestron (CASQ2) Asp398del, and titin (TTN) Lys4455Arg." (PMID 23476865, 2013). "This study investigated whether stabilizing RYR2 could suppress DOX-induced cardiomyopathy (DIC) and identified the optimal duration of dantrolene treatment as a pharmacological method." (PMID 39896128, 2025).
cardiomyopathy (continued). "Our approach was enabled by the development of a correlative imaging protocol that overcomes the broad unavailability of animal models with endogenous fluorescent reporters of either RyR2 and/or [Ca2+]i that can simultaneously model the cellular and molecular basis of cardiomyopathy." (PMID 37220792, 2023). "We found that this variant would lead to a decrease in the level of TNNI3K mRNA and protein, as well as a decrease in the expression of the RYR2 gene, which further proves that TNNI3K plays an important role in cardiomyopathy and expands the spectrum of the TNNI3K variants." (PMID 35274013, 2022). "We identified novel DNVs in diagnostic-grade genes (RYR2, TNNT2, PTPN11, MYH7, LZR1, NKX2-5), and five cases harbouring a combination of prioritised variants, suggesting that oligogenic inheritance and genetic modifiers contribute to cardiomyopathies." (PMID 36357925, 2022). "Given that Speg binds to both RyR2 and SERCA2a, it plays a role in the structural organization of sarcoplasmic reticulum complexes which may explain its implication in cardiomyopathies." (PMID 35563595, 2022). "Although the separate entity ACM has been subsequently questioned as mutations in RYR2 typically lead to exercise or emotion-induced ventricular tachycardia without overt cardiomyopathy, referred to as catecholaminergic ventricular tachycardia (CPVT)." (PMID 32670084, 2020). "Interestingly, RyR2 transcripts containing this exon are upregulated in Rbm20-null rats as well as in cardiomyopathy patients." (PMID 30050558, 2018). "The RyR2:cMyBP-C association could also be relevant in DCM and HCM, cardiomyopathies often accompanied by an arrhythmogenic phenotype." (PMID 29930088, 2018). "In addition, ryanodine receptor 2 (RYR2) has been implicated in both human ARVC and in a chronic anthracycline-induced cardiomyopathy in mice." (PMID 29056678, 2017). "Since CaMKII has emerged as a procardiomyopathic signal, our goal was to determine whether CaMKII inhibition has a protective role in a severe form of cardiomyopathy due to impairment of CaM inhibition of RyR2." (PMID 25093823, 2014). "The mutant channels displayed sub-conductance states and at the lowest conductive state displayed a greatly enhanced Po at pCa7.7, compared to WT (although RyR2 activity of this control may have been compromised by the cardiomyopathy." (PMID 19345240, 2009). "RyR2, purified from an arrhythmogenic right ventricular cardiomyopathy (ARVC) patient heterozygous for G1885E/G1886 and G1885/G1886S, was compared for single channel characteristics to an ARVC patient with a RyR2 WT genotype, but whose heart was removed for transplant for cardiomyopathy." (PMID 19345240, 2009). "Although these RYR2 and MYH7 variants are classified as VUS, based on their association with cardiomyopathies and evidence of high pathogenic scores, we suggest that these variants may negatively impact cardiac output during vigorous exercise and might contribute to the development of EHI." (PMID 39457051, 2024). "Levels of cardiomyopathy-related proteins, cadherin-binding proteins, including PKP2, and Ca2+-handling proteins such as RYR2, SERCA2a, and NCX gradually decreased from control through CH to SCD groups." (PMID 41468454, 2025). "Early treatment with a RyR2 stabilizer prevents an excessive SR Ca2+ leak and DMD-related cardiomyopathy in mice." (PMID 37296659, 2023). "A separate study revealed AAV9-delivered BIN1 increases survival of mice with pressure-overload induced cardiomyopathy using the transverse aortic constriction (TAC) model, normalizing t-tubule membrane intensity and CaV1.2 and RyR2 distribution." (PMID 35069264, 2021). "Based on the understanding of CaMKII as a pathological signaling molecule in cardiomyopathies, we asked whether an active strategy of chronic myocardial-targeted CaMKII inhibition could prevent or reduce cardiac hypertrophy in a mouse model (Ryr2ADA/ADA mice) with a well-defined mutation in RyR2." (PMID 25093823, 2014).
cardiomyopathy (continued). "Interestingly, both RyR2 and CASQ2 mutations may be responsible for cardiomyopathies." (PMID 23476865, 2013). "For example, due to the hypersensitivity to excitation-contraction coupling in cardiomyopathy of DMD patients, targeting RyR2 may offer therapeutic benefit." (PMID 39056750, 2024). "It has been reported that CaMKII hyperphosphorylation of RyR2 accounts for excessive diastolic SR Ca2+ leak in non-ischemic (aortic banding) cardiomyopathy, but not in ischemia (post-MI) in which PKA phosphorylation of RyR2 is involved." (PMID 25425099, 2014). "However, both Ryr2-p.L433P+/– and Ryr2-p.N2386I+/– knock-in mice demonstrated induced atrial fibrillation and leaky calcium channels in the sarcoplasmic reticulum of atrial myocytes but no structural or functional changes of cardiomyopathy." (PMID 32670084, 2020). "The phenotype for each ryanodine receptor disease seems to be unique to the receptor and tissue type; cardiomyopathy is not reported in the phenotypic spectrum of RYR1‐RM; and skeletal myopathy is not reported in the phenotype of RYR2 disease." (PMID 34528764, 2021).
atrial fibrillation (56 papers, 2013 to 2025). A disorder characterized by an electrocardiographic finding of a supraventricular arrhythmia characterized by the replacement of consistent P waves by rapid oscillations or fibrillatory waves that vary in size, shape and timing and are accompanied by an irregular ventricular response. "Diabetes mellitus–associated atrial fibrillation is caused by macrophage IL-1β through mitoROS modulation of RyR2 Ca2+ leak." (PMID 38889387, 2024). "Type 2 ryanodine receptor (RyR2) controls calcium release, and RyR2 mutations have been implicated in atrial fibrillation." (PMID 34062094, 2021). "Li found that abnormal SR Ca2+ leakage via RyR2 is a molecular mechanism underlying atrial fibrillation (AF) progression and long-lasting spontaneous AF (sAF) development." (PMID 31143551, 2019). "Atrial fibrillation was linked to the dysfunction of RYR2, which also produces seven circRNA isoforms in atrium and ten in vena cava." (PMID 28842720, 2017). "In summary this reports showed the first time that decreased local PP1 regulation of RyR2 contributes to RyR2 hyperactivity and promotion of atrial fibrillation susceptibility." (PMID 26617522, 2015). "Cardiac ryanodine receptor mutations are associated with catecholaminergic polymorphic ventricular tachycardia (CPVT), and some, including RyR2-P2328S, also predispose to atrial fibrillation." (PMID 25850710, 2015). "In addition, sudden infant death syndrome (SIDS) and atrial fibrillation (AF) are related to abnormalities of the RyR2 gene, and increasing numbers of patients with RyR2 mutation have been found so far." (PMID 31143551, 2019). "Interestingly, local PP1 regulation of RyR2 resulting in enhanced phosphorylation of the receptor has been proposed to promote atrial fibrillation susceptibility in mice." (PMID 28326667, 2017). "Moreover, alterations in the RyR2 in HF may also contribute to supraventricular defects associated with HF such as sinus node dysfunction and atrial fibrillation." (PMID 34690808, 2021). "A recent study found that in mice with RyR2 mutations leading to diastolic Ca2+ leak, increased RyR2 oxidation, mitochondrial dysfunction and increased ROS production are observed, and these findings were associated with an increase in atrial fibrillation (AF) susceptibility." (PMID 27536244, 2016). "Pediatric patients with RYR2 exon 3 deletion exhibit a peculiar phenotype that includes a rare event of atrial arrhythmias and paroxysmal atrial fibrillation." (PMID 39595626, 2024). "While HF and atrial fibrillation are complex and multi-factorial diseases, there is strong evidence that they share common elements and that diastolic SR Ca2+ leak via RyR2 plays an important role in the progression of both disorders." (PMID 39278969, 2024). "Patients with RYR2 variants also present with multiple phenotypes including sustained ventricular tachycardia, idiopathic ventricular fibrillation, atrial fibrillation (AF) and cardiomyopathies." (PMID 37122207, 2023). "In atrial fibrillation-remodelled hearts, we recently confirmed that inhibition of increased RyR2-mediated [Ca2+]SR leakage by dantrolene can suppress CaT/APD alternans and thereby decrease AF vulnerability." (PMID 36171554, 2022). "WXKL was proved to attenuate sympathetic atrial fibrillation induced by adrenergic activation with the mechanism of modulating neurohormones by inhibiting calmodulin (CaM) expression and ryanodine receptor 2 (RYR2) phosphorylation." (PMID 35677364, 2022). "Recent experimental evidence suggests that the oxidation of ryanodine receptor 2 (RYR2) induces the intracellular release of Ca2+ from the sarcoplasmic reticulum, promoting the establishment of atrial fibrillation." (PMID 35008432, 2021). "However, abnormal RyR2 activity has been linked to the development of arrhythmias, including increased spontaneous Ca2+ release in human atrial fibrillation (AF)." (PMID 33718369, 2021).
atrial fibrillation (continued). "Oxidized CaMKII mediate the phosphorylation of the RYR2, leading to calcium overload and the formation of multiple wavelets triggering atrial fibrillation emergence." (PMID 35008432, 2021). "We identified several potential loci, in particular PHLPP2, BBS9, RyR2, DUSP4 and HSPA8, associated with new-onset of atrial fibrillation, delirium, myocardial infarction, acute kidney injury and stroke after cardiac surgery." (PMID 30678657, 2019). "In particular, RyR2 channel dysfunction was originally identified in the atria of elderly patients with chronic atrial fibrillation and more recently after short-term tachypacing in rabbit atria." (PMID 30349482, 2018). "Very recently the group around Xander Wehrens transferred this knowledge into better understanding of disease mechanisms in atrial fibrillation putatively underlying deregulated PP1/spinophilin interactions and subsequent hyperactivation of RyR2." (PMID 26617522, 2015). "KN-93 blocked pacing induced atrial fibrillation in the Ryr2 R176Q/+ mouse model (Chelu etal., 2009)." (PMID 24600394, 2014). "CaMKII-mediated RyR2 Ca2+ leak is involved in arrhythmogenesis in a large variety of pathological states, including Duchenne muscular dystrophy, chronic β-adrenergic stimulation, atrial fibrillation and arrhythmias resultant from cardiac glycoside treatment." (PMID 34381362, 2021). "Notably, in samples from patients with chronic atrial fibrillation both LCC loss-of-function and RyR2 gain-of-function are now commonly observed." (PMID 30349482, 2018). "Furthermore, increased ROS and abnormal calcium release via alterations in type 2 ryanodine receptor (RyR2) promote atrial fibrillation (AF)." (PMID 40227417, 2025). "Atrial fibrillation (AF) is the most common heart rhythm disorder, and it is characterized by electrical and structural cardiac remodeling that among other factors includes changes in the phosphorylation status of a wide range of proteins, such as RyR2." (PMID 37958665, 2023). "Likewise, in atrial cardiomyocytes from patients with long-standing persistent atrial fibrillation (AF), some studies reported RyR2 dysfunction and increased SCaE incidence, while others showed reduced SCaE incidence and calcium-signaling silencing." (PMID 35406654, 2022). "Two recent studies have demonstrated that TBX5 regulates a network of cardiac channel genes, including RyR2 and SERCA2, to maintain cardiac rhythm, which is involved in atrial fibrillation." (PMID 35167494, 2022). "The leakage of sarcoplasmic reticulum (SR) Ca2+ due to ryanodine receptor 2 (RyR2) PKA hyperphosphorylation may contribute to the development and/or sustenance of atrial fibrillation." (PMID 36826581, 2023). "However, in pAF, there is primarily an increase in SR Ca2+ uptake, opposite to the decrease observed in cAF, and no increase in RyR2 phosphorylation is found, nor is atrial fibrillation-related electrical remodeling observed in pAF cardiomyocytes." (PMID 38028487, 2023). "Similarly, a 1.1 kb deletion of exon 3 in RYR2 was identified in two families with complex phenotypes consisting of CPVT combined with atrioventricular (AV) block, sinoatrial node (SAN) dysfunction, atrial fibrillation (AF), and atrial standstill." (PMID 40710783, 2025).
diabetes (28 papers, 2011 to 2025). "We identified a missense variant in the RyR2 gene that co-segregated with diabetes in six individuals – four sequenced individuals and two non-genotyped individuals (parents of one of the four sequenced individuals)." (PMID 38444585, 2024). "Further studies are needed to investigate the contribution of rare RyR2 missense mutations to diabetes and related phenotypes." (PMID 38444585, 2024). "used a mouse model to demonstrate that a gain-of-function missense mutation in RyR2 that results in constitutive phosphorylation led to basal hyperinsulinemia and other known hallmarks of pre-diabetes." (PMID 38444585, 2024). "In fact, diabetes has been reported to cause changes in RYR2 function leading to contractile dysfunction." (PMID 36804872, 2023). "PTMs by AGEs and ROS cause the variation in RyR2 activity found in preclinical models of diabetes." (PMID 40771931, 2025). "It has been previously shown that the mechanisms underlying the dysfunction of RyR2 in diabetes include, in part, a hyperphosphorylation of RyR2 due to both high phosphorylation levels of both protein kinase A (PKA) and Ca2+-calmodulin kinase II (CaMKII) under hyperglycemia." (PMID 24693334, 2014). "We also found that at equivalent amounts of RyR2 protein from diabetes rats, the heart bound less [3H] ryanodine activity compared with control rats; insulin and Rb1 treatment increased the [3H] ryanodine activity." (PMID 38961333, 2024). "Neutralizing the RyR2 activity significantly decreased in diabetes from control, and increased in Rb1 treatment group from diabetic group." (PMID 38961333, 2024). "We found that although total RyR2 remained significantly unchanged, phosphorylation of RyR2 at Ser2808 increased significantly during diabetes, and these increases were attenuated by insulin and Rb1 treatment." (PMID 38961333, 2024). "The mechanism for Rb1 protecting the myocardia of diabetic rats is reducing or scavenging ROS, RCS production, and RyR2 phosphorylation in diabetes mellitus." (PMID 38961333, 2024). "Although much is known about the RYR2 interactors, less is known about the mechanisms of its downregulation and altered interactions during diabetes." (PMID 36804872, 2023). "Other groups have also investigated the role of RyR2 in insulin secretion patterns in diabetes mellitus." (PMID 34725342, 2021). "Majority of studies in both models of diabetes have shown that the activity of RyR2 is increased, while the activity of SERCA2a is diminished in diabetic ventricular cardiomyocytes." (PMID 33274235, 2020). "The relationship between diabetes-induced decrease in the RyR2 activity and the formation of AGE during chronic diabetes was also shown in other studies." (PMID 33274235, 2020). "It is evident that remodeling the activity of SERCA2a and RyR2 favors the improvement of Ca2+ handling in diabetes." (PMID 33274235, 2020). "In a previous study conducted by the same group on 6-week STZ-diabetic rat hearts, it was shown that the dysfunction of RyR2 stems in part from diabetes-induced increase in its disulfide bond content." (PMID 33274235, 2020). "Abnormally high activity of RyR2 is the most universal finding demonstrated across several models of diabetes." (PMID 30425651, 2018). "Future studies are needed to identify the most suitable approaches for RyR2 stabilization in diabetes." (PMID 30425651, 2018). "Diabetes significantly decreased the ratios of RyR2/T-PLB, SERCA2a/T-PLB, and p-PLB/T-PLB in WT mice (P < 0.05 between WT STZ and WT controls) but not in Tg mice (P > 0.05 between Tg STZ and WT controls)." (PMID 27295516, 2016). "As diabetes progressed, Ca2+ spark properties changed and levels of RyR2, SERCA, NCX1, and FKBP12.6 decreased." (PMID 24712865, 2014). "Reduction in the RyR2 expression induced by uncontrolled diabetes was attenuated with AZL treatment." (PMID 22054019, 2011).